TIFA (TRAF interacting protein with forkhead associated domain)
Description:
Adapter molecule that plays a key role in the activation of pro-inflammatory NF-kappa-B signaling following detection of bacterial pathogen-associated molecular pattern metabolites (PAMPs). Promotes activation of an innate immune response by inducing the oligomerization and polyubiquitination of TRAF6, which leads to the activation of TAK1 and IKK through a proteasome-independent mechanism. TIFA-dependent innate immune response is triggered by ADP-D-glycero-beta-D-manno-heptose (ADP-Heptose), a potent PAMP present in all Gram-negative and some Gram-positive bacteria: ADP-Heptose is recognized by ALPK1, which phosphorylates TIFA at Thr-9, leading to TIFA homooligomerization and subsequent activation of pro-inflammatory NF-kappa-B signaling.
Synonyms: T2BP; MGC20791; T6BP; TIFAA
Tractability: PROTAC: ubiquitination databases record sites on it; its protein half-life has been measured.
Gene: Protein-coding gene on chromosome 4 (112,272,968 to 112,285,955, reverse strand). Ensembl gene ENSG00000145365.
Subcellular location: Cytoplasm
Subcellular location (Human Protein Atlas): Nucleoli; Nucleoplasm; Cytosol
Pathways (Reactome):
Immune System: Alpha-protein kinase 1 signaling pathway; TAK1-dependent IKK and NF-kappa-B activation
Gene Ontology:
Molecular function: protein binding
Biological process: cytoplasmic pattern recognition receptor signaling pathway; innate immune response; positive regulation of canonical NF-kappaB signal transduction; protein homooligomerization; regulation of canonical NF-kappaB signal transduction; signal transduction; tumor necrosis factor-mediated signaling pathway
Cellular component: cytoplasm; ubiquitin ligase complex; cytosol
Genetic constraint (gnomAD): Missense variants: 165 observed, 201.65 expected, observed/expected ratio (o/e) 0.82, 90% interval 0.72 to 0.93. Synonymous variants: 66 observed, 73.63 expected, observed/expected ratio (o/e) 0.9, 90% interval 0.73 to 1.1.
Homologues: Orthologues: chimpanzee TIFA (99% identical), macaque TIFA (97% identical), dog TIFA (87% identical), rabbit TIFA (84% identical), pig TIFA (80% identical), guinea pig TIFA (79% identical), rat Tifa (77% identical), mouse Tifa (77% identical), tropical clawed frog tifa (45% identical), zebrafish tifa (32% identical). Paralogues in human: TIFAB (24% identical).
Diseases named in the same sentence as TIFA in open-access papers:
TIFA is named in the same sentence as 28 diseases in open-access papers, as found by Europe PMC text mining. Sharing a sentence is not in itself a finding about the gene and the disease. The quoted sentences say what the papers report.
ROSAH syndrome (3 papers, 2025). "The transcriptional regulation of TIFA thus appears normal in patients with ROSAH syndrome." (PMID 39868044, 2025).
Sepsis (3 papers, 2025). Sepsis is defined as life-threatening organ dysfunction caused by a dysregulated host response to infection. "NSUN3 and TIFA expressions were upregulated in mice with sepsis-associated acute kidney injury and lipopolysaccharide (LPS)-induced HK-2 cells." (PMID 41462962, 2025). "Eventually, NSUN3 enhanced sepsis-associated acute kidney injury by stabilizing TIFA mRNA through m5C." (PMID 41462962, 2025). "SU3 also stabilizes TIFA mRNA through m5C methylation, and the activated TIFA subsequently initiates the NF-κB pathway, leading to an intensified renal inflammatory response and worsening the condition of sepsis-induced AKI." (PMID 40989844, 2025). "In the mechanism of sepsis-associated acute kidney injury, NSUN3 increased the stability of TIFA mRNA and upregulated its expression through m5C modification." (PMID 41462962, 2025). "Our analysis of the dataset (GSE225192) revealed that, compared with the sham group, mRNA levels of TIFA and IL-1β were significantly elevated in sepsis." (PMID 40385253, 2025).
acute myeloid leukemia (2 papers, 2020 to 2024). Acute myeloid leukemia (AML) is a group of neoplasms arising from precursor cells committed to the myeloid cell-line differentiation. "The expression of TIFA is also increased in acute myeloid leukemia." (PMID 32188695, 2020). "In acute myeloid leukemia (AML), AURKA indirectly activates the NF-κB pathway by phosphorylating TIFA at T9." (PMID 39334449, 2024).
hepatocellular carcinoma (2 papers, 2016 to 2022). A malignant tumor that arises from hepatocytes. "Our previous work showed that TIFA suppresses hepatocellular carcinoma (HCC) progression via apoptosis and cell cycle arrest." (PMID 29263897, 2016). "Likewise, TIFA (TNF receptor associated factor-interacting protein with a forkhead-associated domain), which can sensitize hepatocellular carcinoma (HCC) cells to apoptosis, competes with MALT1 for TRAF6 binding." (PMID 35203553, 2022).
anhidrosis (1 paper, 2025). Lack of sweating or the ability to sweat when provoked by the appropriate stimulus. "ROSAH (retinal dystrophy, optic nerve edema, splenomegaly, anhidrosis, and headache) syndrome is a rare genetic disease caused by variants in alpha-kinase 1 (ALPK1) resulting in downstream pro-inflammatory signaling mediated by the TIFA/TRAF6/NF-κB pathway." (PMID 40925900, 2025).
autoimmune disease (1 paper, 2021). A disorder resulting from loss of function or tissue destruction of an organ or multiple organs, arising from humoral or cellular immune responses of the individual to their own tissue constituents. "Given that the underlying autoimmune disease may confound TIFA protein expression level, we further stratified PAH patients based on their etiologies into idiopathic PAH and CTD-PAH." (PMID 34238983, 2021). "Third, although the present study shows that TIFA is involved in the pathogenesis of PAH, TIFA may not be specific to PAH and could also be elevated in the presence of underlying autoimmune diseases." (PMID 34238983, 2021).
chronic gastritis (1 paper, 2017). Inflammation of the stomach that is chronic in nature. "Taken together, our results indicate that the sequential activation of TIFA, NOD1, and CagA delivery drives the initial inflammatory response in gastric epithelial cells, orchestrating the subsequent recruitment of immune cells and leading to chronic gastritis." (PMID 28811347, 2017).
colitis (1 paper, 2020). Inflammation of the colon. "The top 3 predicted upstream regulators in inactive extensive colitis were miR-155-5p, SOCS1, and TREM1, regulating CXCL2 and SOCS1; CXCL2 and SOCS1; and CXCL2, HES4, and TIFA, respectively." (PMID 32731480, 2020).
gram-negative bacterial infections (1 paper, 2017). Infections caused by bacteria that show up as pink (negative) when treated by the gram-staining method. "Since S. flexneri and S. typhimurium are both gram-negative, these results suggested that TIFA/TRAF6-dependent IL-8 expression was specifically triggered during gram-negative bacterial infections." (PMID 28222186, 2017).
lung carcinoma (1 paper, 2021). "Besides, high expression of TIFA and IL1A as a gene, which regulates tumor growth, angiogenesis, and metastasis in lung carcinoma cell has been reported." (PMID 33765916, 2021).
pneumonia (1 paper, 2022). An acute, acute and chronic, or chronic inflammation focally or diffusely affecting the lung parenchyma, caused by an infection in one or both of the lungs (by bacteria, viruses, fungi, or mycoplasma.). "In the present study, GmhB was dispensable for normal inflammation during pneumonia as determined by immune cell recruitment and cytokines signatures associated with ALPK1/TIFA/NF-κB signaling." (PMID 35762751, 2022).
pulmonary arterial hypertension (1 paper, 2021). Pulmonary arterial hypertension (PAH) is a group of diseases characterized by mean pulmonary artery pressure >20 mmHg and elevated pulmonary arterial resistance leading to right heart failure. "Tumor necrosis factor receptor-associated factor-interacting protein with a forkhead-associated domain (TIFA), a key regulator of inflammation, may be involved in the pathogenesis of pulmonary arterial hypertension (PAH)." (PMID 34238983, 2021).
systemic hypertension (1 paper, 2021). "In addition, the increased expression of TIFA protein in hypertensive subjects also indicates TIFA as a potentially sensitive marker of subclinical inflammation underlying the pathogenesis of PAH as well as systemic hypertension." (PMID 34238983, 2021). "The ex vivo study showed that siRNA-based TIFA protein expression silencing in PBMCs obtained from systemic hypertension or PAH patients resulted in a significant reduction of both IL-1β and TNF-α levels." (PMID 34238983, 2021). "The results not only support the role of inflammation in systemic hypertension but also point out TIFA protein as a sensitive biomarker, adjunctive to other inflammatory mediators, to surrogate the extent of vascular remodeling underlying systemic hypertension." (PMID 34238983, 2021). "It is worth exploring the mechanisms of how TIFA initiates the progression of PAH and systemic hypertension and the feasibility of TIFA as a novel therapeutic target in future studies." (PMID 34238983, 2021).
infection (11 papers, 2007 to 2024). The state of being infected such as from the introduction of a foreign agent such as serum, vaccine, antigenic substance or organism. "Loss of Smac upon Hp-infection and γH2AX-induction were unaltered in TIFA-deficient cells (as a control in HeLa cells, Smac-loss is also shown)." (PMID 35505004, 2022). "We also tested each variant for protection against T2 infection, again finding that RB69 TifA produced the clearest plaques and led to the highest EOP on +toxIN lawns." (PMID 35924892, 2022). "To confirm that this infection requires tifA, we used a CRISPR-Cas9 system to generate two mutant strains of T4 (see ‘Materials and methods’) containing either a 98 bp deletion or 5 bp insertion disrupting the tifA open-reading frame." (PMID 35924892, 2022). "TIFA oligomers were found in both infected and bystander cells, suggesting that TIFA was functionally active in both cell types during infection." (PMID 28222186, 2017). "A co-staining between TIFA and NF-κB p65 showed that TIFA oligomers formed as early as 15 minutes post-infection and seemed to even precede NF-κB activation as visible in some cells." (PMID 28222186, 2017). "TIFA oligomerization was also observed following infection of the Caco-2 cell line, revealing that this process is also a relevant host response to S. flexneri infection in human colonic cells." (PMID 28222186, 2017). "While infection remained comparable, this independent approach confirmed a dramatic inhibition of IL-8 after S. flexneri ΔvirG infection of cells depleted for TIFA and TRAF6." (PMID 28222186, 2017). "Therefore, further studies on the mechanisms and role of ADP-heptose recognition by the ALPK1/TIFA pathway during infections with other pathogens are pending." (PMID 37317291, 2023). "Activation of the NF-κB transcription factor by ADP-heptose through the ALPK1/TIFA pathway induces the expression of inflammatory genes during infections with pathogens such as S. flexneri, S. typhimurium, N. meningitidis, Y. pseudotuberculosis, H. pylori, and C. jejuni." (PMID 37317291, 2023). "The levels of inflammatory cytokines associated with the ALPK1/TIFA/NF-κB axis increased after infection with K. pneumoniae, but this was also independent of GmhB." (PMID 37317291, 2023). "In addition, we identify alpha-kinase 1 (ALPK1) as the critical kinase responsible for TIFA oligomerization and IL-8 expression in response to infection with S. flexneri and S. typhimurium but also to Neisseria meningitidis." (PMID 28222186, 2017). "We tested whether this kinase could also control TIFA oligomerization during infection." (PMID 28222186, 2017). "In contrast, specific mutations in ALPK1 allow it to also be activated by endogenous human nucleotide sugars such as UDP-mannose, leading to the phosphorylation of TIFA in the absence of infection." (PMID 39600973, 2024). "The ALPK1/TIFA/NF-κB axis was also strongly activated during the infection of intestinal cells with C. jejuni, which do not possess such infective systems as T3SS or type IV secretion systems (T4SS) do." (PMID 37317291, 2023). "ALPK1 was then identified as a PRR in infections by Gram-negative bacteria, since its catalytic activity is essential for the self-oligomerization of TIFA." (PMID 35408892, 2022). "AGS cells lacking ALPK1 or TIFA expression were resistant to replication fork slowing in this assay, both in the setting of live infection and of exposure to β-ADP-heptose." (PMID 33037203, 2020). "Depletion of neither TIFA nor TRAF6 had an impact on L. monocytogenes-induced IL-8 production and TIFA failed to form oligomers after infection." (PMID 28222186, 2017). "Altogether, these results show that HBP is a key bacterial PAMP sensed by epithelial cells during infection by both invasive and extracellular gram-negative bacteria and that TIFA/TRAF6-dependent innate immunity against HBP is controlled by ALPK1." (PMID 28222186, 2017).
infection (continued). "Here we demonstrate that the host proteins ALPK1, TIFA and TRAF6 act sequentially to activate the transcription factor NF-κB and regulate the production of chemokines in response to infection by the pathogens Shigella flexneri, Salmonella typhimurium and Neisseria meningitidis." (PMID 28222186, 2017). "Our data suggest that TIFA, NOD1, and CagA all contribute to the NF-κB-driven inflammatory response in gastric epithelial cells; however, how much each of these pathways contributes to natural infection remains an open question." (PMID 28811347, 2017). "This hypothesis was tested by determining whether TIFA and TRAF6 co-localized after infection." (PMID 28222186, 2017). "In addition, infection with the S. flexneri and S. typhimurium ΔhldE mutants failed to induce the oligomerization of TIFA." (PMID 28222186, 2017). "In order to further confirm the functional role of TIFA in HCC, we examined apoptosis in the HCC tumor cell line SK-Hep-1 following TIFA reconstitution by lentivirus for 48 h and after several passages post infection (>7 days) using (PI-Annexin V double staining) flow cytometry." (PMID 29263897, 2016). "Similar results were obtained upon infection with wild-type bacteria as well as in HEK293 cells, showing that the contribution of TIFA and TRAF6 was not restricted to infections with the ΔvirG mutant or with HeLa cells." (PMID 28222186, 2017).
tumor (5 papers, 2015 to 2025). "In fact, this is independent of tumor stage, supporting the notion that loss or suppression of TIFA may be an early step toward tumor development." (PMID 26501855, 2015). "The collective evidence suggested that TIFA expression acted to suppress tumor progression via more than one mechanism." (PMID 26501855, 2015). "In order to determine whether MALT1 also inhibits TIFA-induced apoptosis in vivo, we performed tumor xenograft studies using SK-Hep1-TIFA-shMALT1 cells and SK-Hep1-TIFA-sc cells transplanted into NOD/SCID mice." (PMID 29263897, 2016). "TIFA has been associated with other signaling pathways, most notably, the NF-κB pathway, which promotes oncogenesis and tumor progression via nuclear translocation and activation of target genes." (PMID 26501855, 2015). "Unexpectedly, TIFA expression was associated with significantly decreased Ki-67 reactivity in tumors, indicating that apoptosis may not act alone to limit tumor size." (PMID 26501855, 2015). "To investigate the functional role of TIFA in HCC, we reconstituted either wild-type (WT) TIFA, or an oligomerization defective (TRAF6-binding mutant, TIFAΔ6) into HCC tumor lines." (PMID 26501855, 2015).
bacterial infection (4 papers, 2017 to 2023). "Instead, we found TIFA to be implicated in at least two signaling pathways that link bacterial infection to inflammation." (PMID 28222186, 2017). "Altogether, these results showed that the mechanism of ADPH sensing that occurs during bacterial infection induces the phosphorylation of both TIFA and ALPK1." (PMID 37072480, 2023). "Recently, alpha-kinase 1 (ALPK1) controlling TIFA/TRAF6-dependent innate immunity against bacterial infection is gradually reported." (PMID 32420802, 2020). "As the interaction between these two features occurs once T9 is phosphorylated and is required to trigger TIFA oligomerization, we searched for a kinase acting upstream of TIFA oligomerization in bacterial infection." (PMID 28222186, 2017).
cancer (3 papers, 2015 to 2025). A tumor composed of atypical neoplastic, often pleomorphic cells that invade other tissues. "As shown, a relatively robust expression of TIFA was detectable in normal liver tissues, whereas in contrast, TIFA expression was weakly detected in frank carcinoma." (PMID 26501855, 2015). "Indeed, TIFA can foster HCC apoptosis, and loss of apoptotic sensitivity is a hallmark of cancer." (PMID 26501855, 2015).
cardiovascular diseases (1 paper, 2021). "In the present study, we demonstrated the role of TIFA protein, a transducer that sustains the positive feedback signaling in the TNF-α–NF-κB axis, in the crosstalk between endothelial, smooth muscle, and immune cells following development of cardiovascular diseases in PAH20,26,27." (PMID 34238983, 2021).
TIFA also shares sentences with these, for which no sentence is quoted: acute kidney injury (1 paper); colorectal adenocarcinoma (1); colorectal cancer (1); genetic disease (1); glioma (1); Headache (1); intestinal tumor (1); liver cancer (1); Retinal dystrophy (1); Splenomegaly (1).